GPX4 (glutathione peroxidase 4)
Diseases named in the same sentence as GPX4 in open-access papers (continued):
Sharing a sentence is not in itself a finding about the gene and the disease.
cardiomyopathy (19 papers, 2021 to 2025). A disease of the heart muscle or myocardium proper. "GSH depletion resulting from GPX4 inactivation is an important process in ferroptosis and is implicated in cardiac dysfunction and cardiomyopathy." (PMID 38655715, 2024). "Dysregulation of the antioxidant enzyme GPX4 is linked to cardiomyopathies, emphasizing its significance." (PMID 38540171, 2024). "In doxorubicin (DOX)-induced cardiomyopathy, downregulation of GPX4 and an increase in lipid peroxidation were associated with the formation of DOX-Fe2+ complexes observed in mitochondria." (PMID 35563704, 2022). "Disruption of the GPX4 antioxidant system has been associated with various conditions such as cardiomyopathy and ischemia-reperfusion (I/R) injury." (PMID 35563704, 2022). "GPX4 expression was markedly downregulated during DOX cardiomyopathy, accompanied by increased lipid peroxidation in mitochondria." (PMID 39318361, 2024). "Protein arginine methyltransferase 4 (PRMT4) promoted ferroptosis by inhibiting Nrf2-mediated GPX4 transcription, thus aggravating cardiomyopathy." (PMID 38887622, 2024). "Doxorubicin-induced cardiomyopathy correlated with decreased expression of GPx4 and increased lipid peroxidation, leading to ferroptosis and functional impairment of the left ventricular ejection fraction with increased cardiac fibrosis." (PMID 34579115, 2021). "Enhancing GPX4 activity through selenium supplementation or pharmacological upregulation could provide novel therapeutic avenues for OS-induced cardiomyopathies." (PMID 40427563, 2025). "Importantly, transgenic overexpression of GPX4 ameliorated, whereas heterodeletion of GPX4 exacerbated DOX cardiomyopathy." (PMID 39318361, 2024). "Recent findings on the role of GPx4 in regulating ferroptosis, a type of cell death in response to excess lipid oxidation, suggest that suppression of GPx4 in atherogenesis and in some forms of cardiomyopathy may play a role in disease progression." (PMID 34579115, 2021). "Impairing GPX4 upregulation induced by OXPHOS deficiency through the inhibition of the integrated stress response, by knocking out either the mitochondrial protease OMA1 or its substrate DELE1, aggravates the cardiomyopathy of Cox10-/- mice by decreasing GPX4 to WT levels, thus inducing ferroptosis." (PMID 37505079, 2023). "Overexpression of TMEM43 inhibited LPS-induced ferroptosis with increased levels of SLC7A11 and GPX4, revealing a protective role of TMEM43 against sepsis-induced cardiomyopathy." (PMID 39318361, 2024).
depression (19 papers, 2020 to 2026). "Third, although we demonstrated Gpx4 plays a key role in the effects of EDA, further research is required to investigate the underlying mechanisms of Gpx4-related ferroptosis in depression and anxiety." (PMID 35130906, 2022). "Taken together, our results reveal that nicorandil attenuates depression following TBI via facilitating the SLC7A11/GPX4 axis to suppress hippocampal ferroptosis." (PMID 39739538, 2025). "This is particularly relevant to depression pathophysiology, as Nrf2 dysfunction exacerbates oxidative stress‐induced neuronal atrophy, while GPX4 depletion accelerates ferroptotic death in mood‐regulating circuits." (PMID 40552333, 2025). "One of the key findings of this study is that both mRNA and protein levels of GPX4, SLC3A2, and SLC7A11 were significantly downregulated in the PFC of ELS mice, and that some of these genes were specifically associated with depression-like behaviors." (PMID 41154206, 2025). "The ferroptosis-related IRF1/SLC7A11/GPX4 signaling pathway also plays an important role in depression." (PMID 40177374, 2025). "Future research should prioritise evaluating these inhibitors in preclinical models of depression, examining their effects on ferroptosis markers (e.g., GPX4, PTGS2, lipid ROS), synaptic integrity, and depression‐related behaviours." (PMID 41311024, 2025). "GPX4-mediated ferroptosis-related signaling pathways represent promising targets for the treatment of depression." (PMID 40177374, 2025). "The use of etomidate upregulates the expression of BDNF, Nrf2 and GPX4, thereby inhibiting ferroptosis in hippocampal neurons and improving depression-like states in rats." (PMID 38259274, 2023). "The upregulation of GPX4 is consistent with the recent mechanism revealed of edaravone on depression, and GPX4 knockdown abolished the effect of edaravone treatment." (PMID 35903552, 2022). "Recently the study reported the anti-ferroptosis role of edaravone via the anti-ferroptosis proteins, the Nrf/GPX4 pathway on depression." (PMID 35903552, 2022). "Given Gpx4 plays a crucial role in glutathione metabolism and the involvement of Sirt1 and Nrf2 in MDD, we next sought to examine the role of Sirt1/Nrf2/HO-1/Gpx4 pathway in EDA-related depression and anxiety by WB." (PMID 35130906, 2022). "The risk of depression increased twofold with combined T/T-T/Tgenotypes of NOS2 c1823C > T(rs2297518) and GPx4 c." (PMID 32111088, 2020). "This study is also the first to examine the changes in the level of Gpx4 isoform in an animal model of depression." (PMID 32281745, 2020). "We further propose that each disorder displays a distinct ferroptosis signature, including dopamine quinone-mediated GPX4 loss in PD, AICD-dependent transcriptional reprogramming in AD, and inflammatory-glutamatergic lowering of the ferroptotic threshold in depression and schizophrenia." (PMID 42075884, 2026). "This suggests that regulating the FTH1/TFR1/GPX4 signaling pathway may inhibit ferroptosis as a potential treatment for depression." (PMID 40177374, 2025). "Lastly, blocking GPX4 abolishes the antidepressant effects of EDA, confirming the regulatory role of the Sirt1/Nrf2/HO-1/GPX4 signaling pathway in ferroptosis, with GPX4 serving as a crucial component in the treatment of depression and anxiety via ferroptosis mechanisms." (PMID 40177374, 2025). "The ALKBH5-PRMT2-β-catenin-GPX4 axis is believed to play an important role in promoting LPS (lipopolysaccharide)-induced ferroptosis in microglial cells, providing new insights into the pathogenesis of depression." (PMID 40177374, 2025).
depression (continued). "This suggests that targeting the SLC7A11/GPX4 axis to regulate ferroptosis may offer new therapeutic strategies for TBI‐related depression." (PMID 39739538, 2025). "Given the significant role of ferroptosis in exacerbating post‐TBI complications, our study focuses on exploring whether nicorandil mitigates depression‐like behaviors in a rat model of TBI by activating the SLC7A11/GPX4 axis, thus reducing hippocampal ferroptosis." (PMID 39739538, 2025). "On the other side, anxiety- and depression-like behaviour may be ameliorated by antioxidants via up-regulation of the sirtuin 1 (SIRT1)–nuclear factor erythroid 2-related factor 2 (Nrf2)–haeme oxygenase 1 (HO-1)–glutathione peroxidase 4 (Gpx4) axis." (PMID 37240914, 2023). "The expression levels of GPX4, SLC3A2, SLC7A11, TFR1, and lipid peroxidation markers in the PFC of mice were measured and correlated with depression-like behavioral changes." (PMID 41154206, 2025). "Mechanistically, nicorandil suppresses ferroptosis via promoting the SLC7A11/GPX4 axis in the hippocampus of rats with TBI, thus ameliorating depression‐like symptoms induced by TBI." (PMID 39739538, 2025). "Other studies indicate that increasing the expression of System Xc- and GPX4 can reduce ferroptosis in the PFC of type 1 diabetic mice, thereby alleviating their anxiety and depression-like behaviors." (PMID 41154206, 2025). "This study shows the effects of chronic administration of agomelatine on expression and the methylation status of Sod1, Sod2, Gpx1, Gpx4, Cat, Nos1, and Nos2 in the brain stricture and blood in the chronic mild stress (CMS) animal model of depression." (PMID 32545212, 2020). "The inhibition of ACSL4 by rosiglitazone could significantly attenuate impulsive and depression-like behaviors in MRL/lpr mice, with increased expression of GPX4 and decreased lipid peroxidation indicators in the brain parenchyma." (PMID 40332005, 2025). "However, the therapeutic effect of SSB2 on depression is blocked when GPX4 is knocked out, indicating that SSB2 acts through a GPX4-dependent manner in mediating TLR4/NF-κB pathway, exerting its anti-ferroptosis and anti-neuroinflammatory roles." (PMID 38259274, 2023). "In the LPS-induced depression model, the demethylation function of m6A-modified PRMT2 mRNA is inhibited, resulting in increased expression of PRMT2 in BV2 cells and the hippocampus, while ALKBH5, SLC7A11, and GPX4 expressions decrease, facilitating ferroptosis." (PMID 40177374, 2025). "The study has shown that GPX4 can affect the role of EDA in mouse models of anxiety and depression, which suggests that GPX4-mediated ferroptosis may be a potential mechanism affecting anxiety and depression." (PMID 35910843, 2022).
diffuse large B-cell lymphoma (19 papers, 2020 to 2026). "In a study investigating the association between GPX4 and OS in patients with diffuse large B cell lymphoma (DLBCL), the GPX4-positive group had a significantly poorer prognosis in OS." (PMID 36443446, 2022). "On the other hand, in diffuse large B-cell lymphoma (DLBCL), lower expression of GPX4 and FSP1 is associated with a worse prognosis." (PMID 39594843, 2024). "On the other hand, EZH2 inhibitors impair the occurrence of ferroptosis by upregulating the heat shock protein family A member 5 (HSPA5) and stabilizing GPX4 in diffuse large B-cell lymphoma (DLBCL)." (PMID 39595619, 2024). "The germinal center B-cell-like (GCB) subtype of diffuse large B-cell lymphoma (DLBCL) is highly sensitive to the ferroptosis inducer dimethyl fumarate (DMF) due to low GPX4 expression and high 5-LOX expression." (PMID 40535125, 2025). "Altretamine (hexamethylmelamine) inhibits GPx4 and effectively kills U-2932 diffuse large B-cell lymphoma (DLBCL) cells in vitro." (PMID 39125992, 2024). "Our data are consistent with a recent report, in which GPX4 and TXNRD1 were still expressed in diffuse large B-cell lymphoma cell lines apparently deficient in SECISBP2 immunostaining, although it was not further studied what kind of mutations may have caused the lack of SECISBP2 protein." (PMID 36291713, 2022). "A clinical and experimental study showed that patients with GPX4-positive diffuse large B-cell lymphoma had significantly poor progression-free survival and overall survival compared with those of the GPX4-negative group by immunohistochemistry results." (PMID 37325669, 2023).
injury (19 papers, 2022 to 2026). Damage inflicted on the body as the direct or indirect result of an external force, with or without disruption of structural continuity. "In the mouse model of cerebral hemorrhage, 20-HETE can inhibit the expression of GPX4, thus aggravating oxidative stress, promoting the occurrence and development of iron death, and aggravating acute brain injury." (PMID 40448227, 2025). "Collectively, these findings demonstrate that GPX4 plays a critical role in the hepatoprotective effects of TA against APAP-induced liver injury." (PMID 40051561, 2025). "The nuclear factor erythroid 2-related factor 2 (Nrf2)- glutathione peroxidase 4 (GPx4) axis was involved in carbon tetrachloride (CCl4)-mediated acute liver injury in mice." (PMID 36999078, 2023). "Future studies should investigate the potential of GPX4 activators or other pharmacological agents to further enhance the protective effects of treatments like TA, providing new avenues for the prevention and treatment of drug-induced liver injury." (PMID 40051561, 2025). "Moreover, our study also showed that YAP1 promoted the expression of SLC7A11 and increased the GPX4 and GSH level both in septic liver injury mice and LPS-stimulated LO2 cells, while suppressed the expression of ACSL4." (PMID 36182901, 2022).
osteoarthritis (19 papers, 2022 to 2026). A noninflammatory degenerative joint disease occurring chiefly in older persons, characterized by degeneration of the articular cartilage, hypertrophy of bone at the margins and changes in the synovial membrane. "This nanoplatform enhances joint retention, elevates GPX4 activity, and attenuates osteoarthritis progression, offering a promising disease‐modifying therapeutic strategy." (PMID 41537173, 2026). "In the mice osteoarthritis model, PRDX3 up-regulation also suppressed GPX4 protein expression in the articular tissue of osteoarthritis mice." (PMID 40757971, 2025). "In vivo and in vitro test results suggest that AVI modulates the Nrf2/GPX4/HO-1 signaling pathway to inhibit cartilage cell ferroptosis and alleviate osteoarthritis." (PMID 40093317, 2025). "PRDX3 up-regulation induced GPX4 protein expression and si-PRDX3 suppressed GPX4 protein expression in the in vitro osteoarthritis model." (PMID 40757971, 2025). "It exerted its protective effect by regulating the Nrf2/GPX4/HO-1 signaling axis to inhibit cartilage cell ferroptosis and improve osteoarthritis." (PMID 40093317, 2025). "Due to the role of ferroptosis in inflammation and osteoarthritis, GPX4 was also involved in osteoarthritis." (PMID 38686488, 2024). "In osteoarthritis, icariin inhibits ferroptosis through the Nrf2/System Xc−/GPX4 axis and alleviates synoviocyte damage, suggesting that icariin can be exploited as a novel therapeutic candidate for synovitis." (PMID 36854703, 2023). "Through further research, GPx4 was shown to play an important role in the relationship between osteoarthritis and ferroptosis." (PMID 35941905, 2022). "Notably, our previous research indicated that THBS1 overexpression alleviated surgery-induced osteoarthritis; however, after GPX4 knockout in chondrocytes, THBS1 was unable to effectively reduce osteophyte formation, cartilage loss was exacerbated, and cartilage damage severity increased." (PMID 40475787, 2025). "In this study, the SIRT3 agonist (0.05 μM of SRT 1720 dihydrochloride) was used to induce SIRT3 and GPX4 protein expressions and attenuate the effects of si-PRDX3 on ROS accumulation in the in vitro osteoarthritis model." (PMID 40757971, 2025). "Meanwhile, the SIRT3 inhibitor (10 μM of SRT AGK2) suppressed SIRT3 and GPX4 protein expressions and inhibited the effects of PRDX3 on ROS accumulation in the in vitro osteoarthritis model." (PMID 40757971, 2025). "In bone marrow mesenchymal stem cells, NRF2/GPX4 activation enhances osteogenic capacity under oxidative stress, while in chondrocytes, SIRT1/NRF2/HO-1 signaling mitigates osteoarthritis progression by suppressing ferroptosis." (PMID 41199365, 2025). "For instance, SND1 promotes degradation of GPX4 by destabilizing HSPA5 mRNA and suppressing HSPA5 expression, thus promoting ferroptosis in osteoarthritis chondrocytes." (PMID 38286993, 2024). "GPx4 regulates ferroptosis or oxidative stress and ECM degradation through the MAPK/NF-κB signaling pathway to alleviate the progression of osteoarthritis." (PMID 35941905, 2022).
renal carcinoma (19 papers, 2021 to 2025). A carcinoma arising from the epithelium of the renal parenchyma or the renal pelvis. "Knockdown of GPX4 could result in ferroptosis and an increase in lipid reactive oxygen species, causing cell death in renal carcinoma cells." (PMID 37283794, 2023). "Recent studies have demonstrated that LIFR inhibition with EC359 induces ferroptosis in renal cancer cells by inactivating GPX4 and depleting GSH." (PMID 40075639, 2025). "Collectively, these natural compounds exploit the heightened ferroptotic vulnerability of renal cancer cells through distinct but convergent pathways centered on GPX4 suppression." (PMID 41425591, 2025). "To further clarify the biofunctions of SLC7A11 and GPX4 in renal carcinoma cells, we will perform a series of experiments in vitro in the near future." (PMID 37807410, 2023). "Reduced FA metabolism due to inhibition of β-oxidation renders renal cancer cells highly dependent on the GPX4/GSH pathway to prevent lipid peroxidation and ferroptosis." (PMID 35096573, 2021). "The regulation of renal cancer cells by GPX4 is primarily dependent on ferroptosis, and high GPX4 expression may be associated with renal clear cell carcinoma proliferation and metastasis." (PMID 40969276, 2025). "GPX4 and glutaminase inhibitors can inhibit pyrimidine synthesis and increase ROS levels in VHL-deficient renal carcinoma cells, and the PARP inhibitor olaparib and glutaminase inhibitors can synergistically inhibit the growth of these cells in vivo and in vitro." (PMID 39399506, 2024). "The distinct metabolic profile of renal cancer is intimately associated with its sensitivity to ferroptosis, with multiple molecular mechanisms implicated in the regulation of ferroptosis in renal cancer, including PDIA4, GPX4, KLF2, ACSL3, and AIM2." (PMID 39092291, 2024). "Following this, we constructed GPX4 overexpression (oeGPX4) renal cancer cell lines." (PMID 36246395, 2022). "More importantly, we confirmed that SLC7A11 could promote the proliferation, migration, and invasion of renal cancer cells by enhancing GPX4 output, which in turn inhibits ferroptosis." (PMID 34761566, 2021). "Finally, SLC7A11 promoted the proliferation, migration, and invasion of renal cancer cells by enhancing GPX4 output, which in turn inhibits ferroptosis." (PMID 34761566, 2021). "Lycorine, an Amaryllidaceae alkaloid with low toxicity, reduces GPX4 and elevates ACSL4 in renal cancer cells; these effects are reversed by ferrostatin-1, implicating ferroptosis as a key mechanism." (PMID 41425591, 2025).